LIN28A (lin-28 RNA binding posttranscriptional regulator A)
Diseases named in the same sentence as LIN28A in open-access papers (continued):
Sharing a sentence is not in itself a finding about the gene and the disease.
fatty liver disease (2 papers, 2022 to 2024). A reversible condition wherein large vacuoles of triglyceride fat accumulate in liver cells via the process of steatosis. "While these mice developed fatty liver disease and had increased fibrogenic gene expression, there was no increase in Lin28a or Lin28b expression." (PMID 38875287, 2024).
hypogonadotropic hypogonadism (2 papers, 2015 to 2022). Abnormal ovarian or testicular function due to insufficient hormonal stimulation from the hypothalamic-pituitary axis. "The dissociation of Lin28a and Lin28b expression reported here is reminiscent of the observed changes in the testicular expression of both targets a model of hypogonadotropic hypogonadism in mice." (PMID 26494358, 2015). "A study on a mouse model of hypogonadotropic hypogonadism (Gpr54 KO) showed a lack of LIN28B in testis, while LIN28A-positive cells were present but with reduced total testicular expression." (PMID 35806250, 2022).
lung adenocarcinoma (2 papers, 2020 to 2024). A carcinoma that arises from the lung and is characterized by the presence of malignant glandular epithelial cells. "The result demonstrated that the expression level of LIN28A in tumor tissue was much higher than that of in adjacent normal tissues, and a SUMOylated LIN28A band was clearly detected in lung adenocarcinoma tumor tissue." (PMID 32333719, 2020).
myeloid leukemia (2 papers, 2021 to 2022). A clonal proliferation of myeloid cells and their precursors in the bone marrow, peripheral blood, and spleen. "In murine models, miR-125b overexpression leads to downregulation of Lin28a and the development of myeloid leukemia." (PMID 34732858, 2022). "In conclusion, LIN28A inhibited the CENPE mRNA and protein production, and reduced CENPE mRNA stability in myeloid leukemia cells." (PMID 34868981, 2021).
osteosarcoma (2 papers, 2022 to 2023). A usually aggressive malignant bone-forming mesenchymal neoplasm, predominantly affecting adolescents and young adults. "In addition, the interaction between MALAT1 and LIN28A has been identified in osteosarcoma cells, suggesting potential association of MALAT1 and LIN28A in DN." (PMID 35813614, 2022).
prostate tumor (2 papers, 2012 to 2019). "The expressions of Lin28A and Lin28B enhance PCa stemness and tumorigenesis via the downregulation of Let-7 miRNA, suggesting that the deregulation of Lin28A and Lin28B/Let-7 miRNA axes promotes the acquisition of tumorigenic and CSC-like properties in prostate tumors." (PMID 31530793, 2019).
sarcoma (2 papers, 2013 to 2018). A usually aggressive malignant neoplasm of the soft tissue or bone. "Lin28A is associated with fibroblast and sarcoma cell reprogramming, whereas its homologue Lin28B is associated with hematopoietic cell reprogramming." (PMID 24386298, 2013). "Lin28A, in use with factors of Oct4, Nanog, Sox2, Klf4 and c-Myc, has been found to be able to reprogram sarcoma cells into mature connective cells with concomitant abrogation of tumorigenicity." (PMID 24386298, 2013). "Human regulatory proteins HNRNPA1 (heterogeneous nuclear ribonucleoprotein A1), HNRNPC, HNRNPL, HuR (human antigen R), and protein LIN28A (lin-28 homolog A) were predicted to bind ebv-sisRNA-1 and/or ebv-sisRNA-2; FUS (fused in sarcoma) was predicted to associate with ebv-sisRNA-2." (PMID 29458410, 2018).
acute leukemia (1 paper, 2017). A clonal (malignant) hematopoietic disorder with an acute onset, affecting the bone marrow and the peripheral blood. "Furthermore, miR-128a, a negative regulator of Lin28A, was found overexpressed in AML cells compared with normal precursors, especially in acute promyelocytic leukemia (APL) and in ‘AML with maturation’ (according to 2016 WHO classification of myeloid neoplasms and acute leukemia)." (PMID 28569789, 2017).
autism spectrum disorder (1 paper, 2019). A spectrum of developmental disorders that includes autism, and Asperger syndrome. "Finally, increased levels of LIN28A mRNA, alanine, and cysteine correlated with behavioral dysfunctions, which include autism spectrum disorder, depression or aggressiveness, and the combination of THBS3 with LIN28A and alanine gave a perfect biomarker signature (AUC 1)." (PMID 31235756, 2019).
cardiac hypertrophy (1 paper, 2023). "However, there is also evidence showing that LIN28A promotes pathological cardiac hypertrophy through the same mechanism." (PMID 37569379, 2023).
Cognitive impairment (1 paper, 2022). Abnormal cognition is characterized by deficits in thinking, reasoning, or remembering. "The results of these studies indicate that Lin28a overexpression after BCCAO was associated with cognitive impairment, astrocyte activation, and BBB disruption." (PMID 35453602, 2022). "We suggest that the inhibition of overexpression of Lin28a induced by chronic cerebral hypoperfusion can alleviate VaD-related cognitive impairment by reducing the activation of astrocytes and CCR6 and by ameliorating BBB disruption." (PMID 35453602, 2022). "Thus, blocking Lin28a may alleviate cognitive impairment caused by VaD." (PMID 35453602, 2022).
cortical dysplasia (1 paper, 2016). "The relative expression of LIN28A (3.8–156.9-fold; p = 0.009), LIN28B (4.1–76.9-fold; p = 0.012) and CCND1 (5.7–126.0-fold; p = 0.009) were higher in AT/RT tissues, compared with cortical dysplasia tissues." (PMID 27095948, 2016).
dwarfism (1 paper, 2022). "LIN28A and LIN28B manifest important differences in the phenotypes mediated by their tissue and temporal-specific deficiency, as constitutive loss of LIN28A caused perinatal dwarfism and metabolic dysfunction." (PMID 35806250, 2022).
embryonal tumors of the CNS (1 paper, 2014). "For molecular diagnosis of this tumor category and to distinguish them from other embryonal tumors of the CNS, combined LIN28A IHC and FISH analysis of the 19q13.42 locus are recommended as routine diagnostic markers." (PMID 24337497, 2014).
epilepsy (1 paper, 2024). A brain disorder characterized by episodes of abnormally increased neuronal discharge resulting in transient episodes of sensory or motor neurological dysfunction, or psychic dysfunction. "Collectively, our findings indicate that LIN28A is a potentially novel target for regulation of newborn neuron-associated memory dysfunction in epilepsy by modulating seizure-induced aberrant neurogenesis." (PMID 38193536, 2024). "Taken together, our data demonstrate that LIN28A is a potentially novel regulator of seizure-induced aberrant hippocampal neurogenesis and affects newborn neuron-associated memory function in epilepsy." (PMID 38193536, 2024). "To investigate roles of LIN28A in epilepsy, we generated Nestin-Cre:Lin28aloxP/loxP (conditional KO [cKO]) and Nestin-Cre:Lin28a+/+ (WT) mice to block LIN28A upregulation in all neuronal lineages after acute seizure." (PMID 38193536, 2024). "Because multiple cell types in DG expressed LIN28A after acute seizure, we generated LIN28A-cKO mice in which Lin28a was deleted in all neuronal lineages to examine its role in epilepsy." (PMID 38193536, 2024). "Since 2 major roles of LIN28A are the promotion of cellular growth and survival, our data indicate that LIN28A can play a critical role in the survival of newborn neurons, especially the generation of mature EGCs in epilepsy." (PMID 38193536, 2024). "Interestingly, sham-manipulated WT and cKO animals showed similar intact PS capability, suggesting a specific role of LIN28A in epilepsy." (PMID 38193536, 2024). "Collectively, our results demonstrate that LIN28A deletion in all neuronal lineages can alter serotonin-mediated signaling after SE, and this can alleviate seizure-induced aberrant neurogenesis and PS memory deficit in epilepsy." (PMID 38193536, 2024). "Finally, we confirmed that HTR4 immunoreactivity was observed in LIN28A-expressing cells in SGZ at 3 days after SE, suggesting that HTR4 can be a potential LIN28A-downstream target in epilepsy." (PMID 38193536, 2024). "Finally, we confirmed that the immunoreactivity to serotonin receptor 4 (HTR4) was colocalized in LIN28A-expressing cells, suggesting HTR4 as a potential LIN28A-downstream target in epilepsy." (PMID 38193536, 2024).
fibroma (1 paper, 2017). A non-metastasizing neoplasm arising from the fibrous tissue. "LIN28A, on the other hand, was overexpressed in all histotypes with the highest expression being seen in HG-S (mean = 10.6; median = 2.32) followed by thecofibromas and fibromas, both with a mean of 10 and a median of 5 and 1.5, respectively." (PMID 28423547, 2017).
hypothyroidism (1 paper, 2015). Abnormally low levels of thyroid hormone. "For this reason, we studied testicular expression of Lin28a and Lin28b mRNAs and let-7a, let-7b, mir-145 and mir-132 miRNAs in models of GH deficiency, hypothyroidism and in adrenalectomized rats." (PMID 26494358, 2015).
intracerebral hemorrhage (1 paper, 2022). A cerebrovascular disorder characterized by bleeding into one or both cerebral hemispheres including the basal ganglia and the cerebral cortex. "Lin-28 is transiently upregulated after intracerebral hemorrhage, and overexpression of Lin28a causes astrocyte hyperplasia." (PMID 35453602, 2022).
keratosis (1 paper, 2024). A skin disorder consisting of hypertrophy of the stratum corneum of the skin. "For expanded gene families, we found three genes were associated with skeletal development and/or bone density (HNRNPH1, LIN28A, and TARP) and two genes (FTH1 and KDSR) were related to keratosis." (PMID 39092175, 2024).
kidney damage (1 paper, 2024). "To summarize, our findings demonstrate that in specific cellular contexts, Lin28A OE can lead to a severe inflammatory response, resulting in significant kidney damage." (PMID 39113694, 2024). "We demonstrated that Lin28A OE in non-hematopoietic lineage can trigger an inflammatory response via the rapid upregulation of several cytokines, including CXCL1 and CCL2, leading to severe kidney damage." (PMID 39113694, 2024).
lissencephaly type 2 (1 paper, 2025). "This phenotype resembles human cobblestone lissencephaly (type 2) and highlights novel implications of the oncogene LIN28A in extracellular matrix integrity." (PMID 40680886, 2025).
male infertility (1 paper, 2024). The inability of the male to effect fertilization of an ovum after a specified period of unprotected intercourse. "The conditional ablation of NRF1 in gonocytes dramatically down-regulates several germline genes (Dazl, Lin28a, Ddx4), blocks germ cell proliferation, and subsequently leads to male infertility in mice suggesting an important role of NRF1 in regulation of some GRRs." (PMID 38715099, 2024).
mesenchymal tumors (1 paper, 2020). "In many other mesenchymal tumors, activated LIN28A or LIN28B RNA-binding protein homologues directly interact with the terminal loop region of either pre-let-7 and/or primary let-7, preventing their biogenesis and tumor repressive function, and can induce their degradation." (PMID 32365712, 2020).
microcephaly (1 paper, 2022). A congenital or acquired developmental disorder in which the circumference of the head is smaller than normal for the person's age and sex. "Loss of the RBP LIN28A leads to microcephaly in mice and a double deletion of LIN28A/B leads to neural tube defects." (PMID 35735914, 2022).
oral cancer (1 paper, 2013). "Recently, Hayashi mentioned expression of Lin28A in side population of TOSCC23 oral cancer cell line." (PMID 24386298, 2013). "Recent study mentioned expression of Lin28A in side population of oral cancer cell lines, and overexpression of Lin28A in TOSCC23 promoted cell malignancy." (PMID 24386298, 2013). "But in consideration of the similarity of Lin28A and Lin28B, we reserved functions of both proteins in oral cancer cell malignancy." (PMID 24386298, 2013). "In contrary, we found high expression of Lin28A in most primary oral cancer cells in clinical specimens." (PMID 24386298, 2013).
ovarian insufficiency (1 paper, 2012). "We hypothesized that LIN28A could regulate primordial germ cell formation and expansion of the germ cell pool, and that disruption of LIN28A might lead to germ cell depletion and primary ovarian insufficiency (POI) in humans." (PMID 22240064, 2012).
renal fibrosis (1 paper, 2022). A final common manifestation of a wide variety of chronic kidney diseases characterized by glomerulosclerosis and tubulointerstitial fibrosis. "LIN28A is associated with dorsal root ganglion neuron apoptosis and renal fibrosis." (PMID 35979430, 2022).
Rett syndrome (1 paper, 2021). A severe neurodevelopmental disorder affecting the central nervous system. "We speculate that LIN28A upregulation, which has been reported to be associated with disease states such as Rett syndrome or cancer and trophic responses, might perturb the molecular interaction network, thereby interfering with the stress response." (PMID 34816099, 2021). "We hypothesized that LIN28A upregulation, observed under pathogenic states such as Rett syndrome or cancer or during the trophic response, may affect subcellular distribution of its interactors by perturbing the protein interaction network." (PMID 34816099, 2021). "Rett syndrome is a devastating neurodevelopmental disorder, and a recent study reported that induced pluripotent stem (iPS) cell-derived neural progenitor cells (NPCs) from patients with Rett syndrome exhibit aberrant up-regulation of LIN28A and lower glia-to-neuron ratio upon differentiation." (PMID 34816099, 2021). "The interactions and pathways described may best fit in the context of neural development as we used the human iPS cell-derived NPC, a model previously used to discover the abnormal upregulation of LIN28A in Rett syndrome." (PMID 34816099, 2021).
Seizure (1 paper, 2024). A seizure is an intermittent abnormality of nervous system physiology characterized by a transient occurrence of signs and/or symptoms due to abnormal excessive or synchronous neuronal activity in the brain. "Seizure-induced LIN28A protein expression pattern and its cellular phenotypes in the DG." (PMID 38193536, 2024).
sickle cell anemia (1 paper, 2014). "Taken together, these data show that transgenic expression of LIN28A in erythroblasts from pediatric subjects with sickle cell anemia regulates both fetal and beta (sickle)-globin expression with comparable ex vivo differentiation of the cells." (PMID 25188417, 2014).
small cell carcinoma (1 paper, 2021). A neuroendocrine carcinoma composed of small malignant cells which are often said to resemble "oat cells" under the microscope. "Cancer de-differentiation transforms luminal-like (differentiated) adenocarcinoma into less luminal-like and more stem-like (undifferentiated) small cell carcinoma through a sequential activation of stem cell transcription factors (scTF) POU5F1, LIN28A, SOX2 and NANOG." (PMID 34911496, 2021).
status epilepticus (1 paper, 2024). Status epilepticus is defined as a continuous seizure lasting more than 30 min, or two or more seizures without full recovery of consciousness between any of them. "Here, using a mouse model of pilocarpine-induced status epilepticus (SE), we characterized spatiotemporal expression of Lin28a mRNA and proteins after SE." (PMID 38193536, 2024). "Therefore, in the present study, we first assessed the spatiotemporal expression patterns of Lin28a mRNA and protein after pilocarpine-induced status epilepticus (SE); we then performed phenotypic analysis of LIN28A induction after acute seizure." (PMID 38193536, 2024).
teratocarcinoma (1 paper, 2014). A germ cell tumor characterized by the presence of an embryonal carcinoma component and a teratoma component. "Using immunocytochemistry on mouse teratocarcinoma P19 cells, we found that Lin28a and Trim25 colocalize in vivo, supporting their functional link." (PMID 25457611, 2014). "To determine whether Trim25 plays a role in Lin28a-mediated uridylation, we performed Trim25 RNAi in mouse teratocarcinoma P19 cells." (PMID 25457611, 2014).
testicular tumors (1 paper, 2022). "LIN28A and LIN28B might present potential targets for developing new therapies in the treatment of fertility but also testicular tumors." (PMID 35806250, 2022).
vascular dementia (1 paper, 2022). A degenerative vascular disorder affecting the brain. "Vascular dementia (VaD) was induced in 12-week-old male Wistar rats using permanent bilateral common carotid artery occlusion (BCCAO), and these rats were treated with Lin28a siRNA on the fourth and seventh day after BCCAO." (PMID 35453602, 2022).